USP4 (ubiquitin specific peptidase 4)
Diseases named in the same sentence as USP4 in open-access papers (continued):
Sharing a sentence is not in itself a finding about the gene and the disease.
colorectal cancer (16 papers, 2017 to 2025). A primary or metastatic malignant neoplasm that affects the colon or rectum. "USP4 has been associated with many human malignant tumors, including brain cancer, liver cancer, colorectal cancer, and melanoma." (PMID 37624791, 2023). "Deubiquitinating PRL-3 by USP4 leads to AKT activation and E-cadherin reduction in colorectal cancer, where an elevated level of USP4 is associated with tumor size, differentiation, distant metastasis, and poor survival." (PMID 33681193, 2021). "To confirm that USP4 is involved in tumorigenesis, we generated USP4 knockout mice and investigated the role of USP4 in colorectal cancer using the established mouse model of colitis-associated colorectal tumorigenesis." (PMID 30514904, 2019). "In CRC, USP4 has been shown to promote colorectal cancer cell metastasis in vitro and in vivo by regulating the stability and activity of β-catenin and PRL-3." (PMID 39922805, 2025). "Similarity, USP4 also acts as an oncoprotein to regulate β-catenin deubiquitination in colorectal cancer." (PMID 37726816, 2023). "Neutral red, a selective inhibitor of USP4, has shown a significant effect on suppressing colorectal cancer progression." (PMID 36694209, 2023). "USP20 and USP4 induce drug resistance in breast cancer and colorectal cancer cells by stabilizing β-catenin, the key modulator of the Wnt pathway." (PMID 36694209, 2023). "USP4 is related to colorectal cancer since the overexpression of USP4 exists in many types of tumors, thus it is considered to be a potential oncogene." (PMID 33498168, 2021). "Β-catenin is a substrate of USP4, and this interaction affects the tumorigenicity of colorectal cancer, as well as brain metastasis in lung adenocarcinoma." (PMID 33681193, 2021). "USP4 facilitates colorectal cancer progression by deubiquitinating and stabilizing β-catenin from its degradation which activates its downstream signaling pathways." (PMID 32669974, 2020). "In contrast, increased expression of USP4 was found in tissue samples from hepatocellular carcinoma, melanoma, esophageal cancer, and colorectal cancer, and USP4 was shown to be oncogenic in these cancer cells." (PMID 31936290, 2020). "USP4 overexpression promoted the level of pAKT in colorectal cancer and this process can be blocked by knockdown of phosphatase of regenerating liver-3 (PRL-3) which can be deubiquitinated and stabilized by USP4." (PMID 32669974, 2020). "Importantly, the interaction of CENPF and USP4 then controlled the invasion and migration of colorectal cancer." (PMID 39922805, 2025). "Recent studies found that USP4 is often overexpressed in various cancers, such as glioblastoma, liver cancer, colorectal cancer, and melanoma, but its role in gastric cancer is unknown." (PMID 37624791, 2023). "USP4 also positively regulated WNT/β-catenin signaling in colorectal cancer." (PMID 30335615, 2018). "USP4 accelerates the growth, invasion, and metastasis of colorectal cancer." (PMID 28473662, 2017). "Thus, we speculate that CENPF is a key downstream target of USP4 in regulating colorectal cancer metastasis." (PMID 39922805, 2025).
glioblastoma (10 papers, 2014 to 2023). The most malignant astrocytic tumor (WHO grade IV). "The role of USP4 in glioblastoma was confirmed since its HR value was the highest in the signature." (PMID 35774799, 2022). "In other cancer entities, high USP4 mRNA was a positive prognostic marker in lung adenocarcinoma and a negative prognostic marker in glioblastoma patients." (PMID 37308746, 2023). "USP4 promotes liver cancer metastasis by upregulating TGF-β signaling to induce the epithelial-mesenchymal transition and activate the ERK pathway by regulating TGF-β to promote the development of glioblastoma." (PMID 34179009, 2021).
lung adenocarcinoma (10 papers, 2016 to 2023). A carcinoma that arises from the lung and is characterized by the presence of malignant glandular epithelial cells. "In patients with lung adenocarcinoma, an elevated level of USP4 transcripts has been clearly associated with a reduced survival." (PMID 36144645, 2022). "For instance, expression of USP4 was downregulated in lung adenocarcinoma, and low USP4 expression was associated with poor overall survival and recurrence-free survival." (PMID 31936290, 2020). "USP4 is the first deubiquitinating enzyme identified in mammalian cells and is frequently overexpressed in various cancers, including lung adenocarcinoma and glioblastoma." (PMID 32549341, 2020). "We further examined the clinical correlation between USP4 and Twist1 using tissue microarrays of lung adenocarcinoma." (PMID 32549341, 2020). "Compared to adjacent tissues, expression of both USP4 and Twist1 proteins were high in biopsy specimens of lung adenocarcinoma patients." (PMID 32549341, 2020). "Taken together, our results indicate that USP4 is a promising therapeutic target for brain metastasis in patients with lung adenocarcinoma." (PMID 26883469, 2016). "Based on these results, we found that USP4 regulated the migratory and invasive abilities of PC14PE6/LvBr4 cells, demonstrating that USP4/β-catenin controls the metastatic potential of lung adenocarcinoma cells." (PMID 26883469, 2016). "At present, studies have shown that USP4, EIF2AK3 and CTCFL genes are related to the prognosis of lung adenocarcinoma." (PMID 35785155, 2022). "We also found that knockdown of USP4 prolonged overall survival (OS) and brain metastasis-free survival (BMFS) of lung adenocarcinoma-bearing mice (respectively, all Log rank p < 0.001), suggesting that USP4 promotes the metastatic abilities of lung adenocarcinoma cells." (PMID 26883469, 2016). "Lung adenocarcinoma patients with a high USP4 status more commonly had no lymph node metastases." (PMID 37308746, 2023).
melanoma (10 papers, 2018 to 2025). A malignant, usually aggressive tumor composed of atypical, neoplastic melanocytes. "These USP4-associated pathways are vital in the pathogenic role of melanoma; however, they remain to be explored." (PMID 35884430, 2022). "Concurrently, the colony formation assay also revealed that USP4 deficiency had little impact on the clonogenic ability of melanoma cells." (PMID 29542252, 2018). "Consistently, the expressions of pro‐apoptotic cleaved‐caspase‐9 and Bax were increased in cisplatin‐treated melanoma cells with USP4 deficiency, whereas the expression of anti‐apoptotic Bcl‐2 was deceased." (PMID 29542252, 2018). "Several USPs, such as USP4 and USP7, have been implicated in promoting melanoma development, highlighting the essential roles of ubiquitination regulators in this disease." (PMID 40788071, 2025). "Altered USP4 expression inhibits the invasion and migration capacity of melanoma cells with a drastic decrease in N-cadherin and an increase in E-cadherin mRNA and protein, both markers of epithelial–mesenchymal transition (EMT)." (PMID 35884430, 2022). "Our transwell assay showed that the knockdown of USP4 remarkably reduced both the invasive and migratory capacity of melanoma cells." (PMID 29542252, 2018). "Thereafter, to investigate the biological function of USP4 in melanoma, we employed lentiviral transfection to obtain stable knockdown of USP4 expression in both A2058 and 451Lu cell line, and the knockdown efficiency was confirmed by western blotting." (PMID 29542252, 2018). "To sum up, we demonstrated that the up‐regulated USP4 plays an oncogenic role in melanoma by simultaneously suppressing stress‐induced cell apoptosis and facilitating tumour metastasis." (PMID 29542252, 2018). "Altogether, our results demonstrate that the up‐regulated USP4 plays an oncogenic role in melanoma by simultaneously suppressing stress‐induced cell apoptosis and facilitating tumour metastasis." (PMID 29542252, 2018). "In the present study, we first found that the expression of USP4 was remarkably up‐regulated in both melanoma cell lines and tissues, and USP4 expression was higher in metastatic melanoma than that in primary one." (PMID 29542252, 2018). "In the present study, we first found that the expression of USP4 was dramatically increased in both melanoma tissues and cell lines compared with benign nevus tissues and NHEM, respectively." (PMID 29542252, 2018). "Subsequently, we showed that the knockdown of USP4 had little effect on melanoma cell proliferation and colony formation under normal condition." (PMID 29542252, 2018). "Herein, we first found that the expression of the deubiquitinase USP4 was significantly up‐regulated in melanoma tissues and cell lines." (PMID 29542252, 2018). "The mRNA expression of USP4 was significantly higher in metastatic melanoma compared with that in primary melanoma in TCGA database, further confirming our results in both melanoma cell lines and tissues." (PMID 29542252, 2018). "In summary, our results demonstrate that USP4 is significantly increased in melanoma and plays an oncogenic role by simultaneously inhibiting stress‐induced cell apoptosis and promoting tumour metastasis." (PMID 29542252, 2018). "Collectively, these data demonstrated that USP4 promotes melanoma cell migration and invasion by promoting EMT." (PMID 29542252, 2018).
melanoma (continued). "Our results showed that USP4 expression was nearly undetectable in nevus tissues, whereas it was significantly increased in melanoma tissues." (PMID 29542252, 2018). "Our subsequent function study revealed that the intervention of USP4 expression had little impact on melanoma cell proliferation and colony formation." (PMID 29542252, 2018). "More importantly, the intensity of USP4 in metastatic melanoma tissues was markedly higher than in primary ones, which was in line with the results in melanoma cells." (PMID 29542252, 2018). "Taken together, these results showed that USP4 was able to protect melanoma cells from cisplatin‐induced apoptosis, thus inducing melanoma tolerance to cisplatin treatment." (PMID 29542252, 2018). "Altogether, our results demonstrate that the up‐regulated USP4 plays an oncogenic role in melanoma by simultaneously inhibiting stress‐induced cell apoptosis and facilitating tumour metastasis." (PMID 29542252, 2018). "Impairing the expression of USP4 inhibits the invasive and migratory ability of melanoma cells." (PMID 33800394, 2021). "It was found that the expression of the USP4 was upregulated in melanoma tissues and cell lines." (PMID 33800394, 2021). "Taken together, these results demonstrated that USP4 expression was up‐regulated in melanoma, indicating that USP4 may act as an oncogene." (PMID 29542252, 2018). "In line with previous studies, we also showed that USP4 promoted melanoma metastasis by suppressing E‐cadherin expression and increasing N‐cadherin expression, indicating the ubiquitous existence of the crosstalk between USP4 and EMT in different kinds of cancer." (PMID 29542252, 2018). "Moreover, we found that USP4 was also able to potentiate the invasive and migratory capacity of melanoma cells by promoting epithelial–mesenchymal transition." (PMID 29542252, 2018). "In addition, the corresponding wound assays also revealed the delayed wound closure in melanoma cells with USP4 knockdown, which was line with the observations in the transwell assay." (PMID 29542252, 2018). "More importantly, USP4 could accentuate the invasive and migratory capacity of melanoma cells by promoting epithelial‐mesenchymal transition." (PMID 29542252, 2018). "Notably, the overall USP4 expression was higher in metastatic melanoma cells than that in primary ones." (PMID 29542252, 2018). "Therefore, apart from the anti‐apoptotic effect in response to cisplatin, USP4 was also important in promoting the invasion and migration of melanoma cells." (PMID 29542252, 2018). "To explore the role of USP4 in melanoma, we first examined the mRNA and protein level of USP4 in a panel of melanoma cell lines at different clinical stages (WM793B, WM35 at primary stage and A2058, A375, 451Lu at metastatic stage), as well as in normal human melanocyte (NHEM)." (PMID 29542252, 2018). "A recent study confirmed that upregulated USP4 plays an oncogenic role in melanoma." (PMID 30335615, 2018). "Furthermore, we performed immunofluorescence staining analysis for detection of USP4 expression in a cohort of 23 melanoma tissues (11 tissues of primary stage and 12 tissues of metastatic stage), as well as in 10 nevus tissues." (PMID 29542252, 2018). "In consistent, our real‐time quantitative reverse transcription‐PCR (qRT‐PCR) assay also revealed that the mRNA level of USP4 was prominently up‐regulated in melanoma cell lines, and USP4 expression was slightly higher in metastatic cells than that in primary ones at the transcriptional level." (PMID 29542252, 2018). "Since that the up‐regulation of USP4 expression was more prominent in metastatic melanoma, we further investigated whether USP4 could affect the migration and invasion of melanoma cells." (PMID 29542252, 2018).
melanoma (continued). "Hence, inhibition of USP4 could be not only a potential therapeutic approach for melanomas with high metastatic ability, but also a sensitizer for melanomas that are tolerant to conventional chemotherapeutic agent, especially cisplatin." (PMID 29542252, 2018). "Furthermore, although USP4 knockdown had little impact on melanoma cell proliferation, it could increase the sensitivity to DNA damage agent cisplatin." (PMID 29542252, 2018). "Moreover, our results showed that USP4 could enhance the invasive and migratory capacity of melanoma cells through the induction of EMT." (PMID 29542252, 2018). "Nevertheless, whether USP4 is aberrantly expressed and plays a pathogenic role in melanoma have not been investigated." (PMID 29542252, 2018). "Our western blotting analysis showed that the USP4 expression was markedly increased in melanoma cells compared with that in NHEM, though the expression level varied a lot in different melanoma cell lines." (PMID 29542252, 2018). "Our cell counting kit‐8 (CCK8) assay showed that the proliferative rate of melanoma cells was not altered after USP4 knockdown." (PMID 29542252, 2018). "More importantly, although USP4 was not essential for the proliferation of melanoma cells, it could exert its tumour‐facilitating role via the suppression of cell apoptosis and the promotion of invasive and migratory ability." (PMID 29542252, 2018).
hepatocellular carcinoma (9 papers, 2014 to 2022). A malignant tumor that arises from hepatocytes. "While other studies suggest that USP4 over‐expression promotes the progress of fibrosis in the liver, as well as the metastasis of hepatocellular carcinoma." (PMID 33295107, 2021). "USP4 deficiency intensifies the inflammation and fibrosis progress in the liver of hepatic I/R injury and NAFLD, While the results were reversed hepatocellular carcinoma." (PMID 33295107, 2021). "TβRI stabilized downstream from TGF-β signaling causes the phosphorylation of Smad2 and 3, the transcription factors responsible for target gene induction, as verified by our result that USP4 fortified Smad2 phosphorylation and promoted migration and proliferation of hepatoma cell." (PMID 24798342, 2014). "For example, USP4 is only expressed in the cytoplasm of HepG2 [human hepatocellular carcinoma (HCC)] cells, while being exclusively nuclear in Saos-2 (human osteosarcoma) cells." (PMID 33681193, 2021). "Another study reported that USP4 is overexpressed in hepatocellular carcinoma (HCC) tissues." (PMID 33664230, 2021). "In addition, USP4 can directly interact with TGF-β receptor type I (TGFR-1) through deubiquitination and activate the TGF-β signaling pathway, which can induce EMT in hepatoma cells, providing a new therapeutic target for the treatment of HCC." (PMID 35875077, 2022). "However, the mechanisms by which USP4 facilitates tumor development, especially in hepatocellular carcinoma (HCC), remain unclear." (PMID 29396555, 2018).
colon cancer (8 papers, 2018 to 2025). "In the realm of colon cancer, this symphony takes on a deeper resonance as up-regulated USP4 and β-catenin herald the crescendo in colon cancer tissues." (PMID 40034124, 2025). "The removal of USP4 from the equation triggers a harmonious reduction in the invasion and migration abilities of colon cancer cells, showing USP4's potential as a target for future anticancer therapies." (PMID 40034124, 2025). "In colon cancer, a deubiquitinating enzyme USP4 suppressed anti-tumor immune responses by deubiquitinating TRAF6 and IRF3, hindering the nuclear localization of the latter protein and thus inhibiting cellular interferon responses and antigen presentation." (PMID 40183093, 2025). "There is a positive correlation between the levels of USP4 and β-catenin in human colon cancer tissues." (PMID 32268558, 2020). "The expression of USP4 and β-catenin was found to be enhanced in colon cancer tissues from patients." (PMID 32486158, 2020). "Knockdown of USP4 in a colon cancer cell line decreased invasion and migration activity, indicating that USP4 is a positive regulator of β-catenin and is a potential target for anti-cancer therapeutics." (PMID 33158118, 2020). "Neutral red (NR) has been reported as a USP4 inhibitor in colon cancer." (PMID 37949874, 2023). "USP4 positively regulates Wnt/β-catenin signaling in colon cancer." (PMID 33158118, 2020). "In addition, USP4 knockdown in a colon cancer cell line resulted in decreased invasion and migration." (PMID 32486158, 2020). "Further, knockdown of USP4 reduces invasiveness and migration in colon cancer cells." (PMID 32268558, 2020). "NR could promote the ubiquitination and proteasomal degradation of endogenous β-catenin via impairing the deubiquitinating activity of ubiquitin-specific protease 4 (USP4) in colon cancer cells." (PMID 33014840, 2020). "It has recently been reported that USP4 directly interacts and de-ubiquitinates HDAC2 resulting in its stability in colon cancer cells." (PMID 30071870, 2018).
head and neck squamous cell carcinoma (8 papers, 2018 to 2024). A squamous cell carcinoma that arises from any of the following anatomic sites: lip and oral cavity, nasal cavity, paranasal sinuses, pharynx, larynx, and salivary glands. "In head and neck squamous cell carcinoma, USP4 can abrogate receptor-interacting protein 1 (RIP1)-induced NF-κB signaling pathway activation by targeting K63-linked polyubiquitination of RIP1 which promotes TNFα induced cell apoptosis." (PMID 32669974, 2020). "An association between USP4 and RIP1 was reported to impair NF-κB activation and exacerbate TNF-α–induced apoptosis in head and neck squamous cell carcinoma (HNSCC)." (PMID 33681193, 2021). "In addition, USP4 plays a tumor suppressor role in head and neck squamous cell carcinoma (HNSCC) by negatively regulating RIP1-mediated NF-κB activation and promoting TNF-α-induced apoptosis." (PMID 30335615, 2018).